SPP1 (secreted phosphoprotein 1)
Diseases named in the same sentence as SPP1 in open-access papers (continued):
Sharing a sentence is not in itself a finding about the gene and the disease.
tumor (continued). "Consequently, the desmoplastic microenvironment could potentially be regulated by the interaction between CSC and Macro_SPP1, leading to the limitation of immune cell infiltration into the tumor core." (PMID 38521868, 2024). "Compared with its precursor inflammatory monocyte TAM3_VCAN, TAM1_SPP1 enriched in metastatic lymph nodes has lower antigen‐presenting ability, but potentially remodels the immune microenvironment by suppressing T cell activation, possibly favoring early tumor cell lymph node colonization." (PMID 39236316, 2024). "Finally, the expression of Spp1 by macrophages showed a significant correlation with tumor weight." (PMID 39372792, 2024). "Meanwhile, SPP1 signaling pathway which involved in tumor growth and metastasis was activated in vascular fibroblast by macrophage, indicating macrophage may help mediate tumor proliferation." (PMID 39440065, 2024). "Research indicates that SPP1 influences the polarisation state of macrophages, and the interaction between SPP1 and macrophages may play a crucial role in the chemotherapy response of tumours." (PMID 38982317, 2024). "Our findings suggested that high levels of CDKN2A, BIRC5, and SPP1 were associated with poor overall survival in patients with HCC, suggesting that BIRC5, CDKN2A, and SPP1 are associated with HCC progression and could be used as tumor biomarkers in patients with HCC." (PMID 39042294, 2024). "Notably, SPP1 serves as both a marker gene for TAM and a hallmark gene for tumor EMT." (PMID 38888512, 2024). "We also analyzed the effect of SPP1 on prognosis in 33 cancers and found that high expression of SPP1 was positively associated with poor prognosis in most cancers, suggesting that cell communication of TAM with tumor epithelial cells via SPP1 may lead to tumor progression." (PMID 38648200, 2024). "Moreover, SPP1 is recognized as a pivotal factor influencing the tumor microenvironment landscape." (PMID 39529085, 2024). "The transition from FOLR2+ macrophages to SPP1+ subsets may represent an adaptation to the microenvironmental stressors, such as hypoxia, which is prevalent in the leading‐edge area due to the high proliferative rate of tumor cells." (PMID 39716897, 2024). "Mast cells in our cohort may also have a potential recruitment effect on SPP1+ macrophages; however, due to their abundance, we cannot determine whether they play a major role, and it is possible that we have underestimated their function in tumor immunity." (PMID 39716897, 2024). "Furthermore, SPP1+ macrophages were found to interact with tumor-reactive CD8+ T cells in humans." (PMID 39372792, 2024). "Moreover, patients with high nuclear SPP1 expression have a low tumor grade (p = 0.007)." (PMID 38067407, 2023). "Moreover, SPP1+ TAMs were found to be positively related to angiogenesis and tumor metastasis." (PMID 36950551, 2023). "Therefore, the expression of Il6, Nos2, Ccl2, Spp1, Tnf, Acat2, Aox1, Crem, Gls2, Per3, Pink1, Txnip, and Ypel3 was examined in acidosis upon simultaneous transfection with microRNA mimics or antagomirs in two tumor lines in vitro and in vivo." (PMID 38069241, 2023). "In addition, MDSC could interplay with SPP1+ TAMs via the LR pair CCL3/CCL3L3-CCR1, which might facilitate the recruitment of SPP1+ TAMs in tumor tissue." (PMID 37475874, 2023). "Additionally, we also revealed the potential interacting proteins and enrichment pathways that may orchestrate the tumor-promoting role of SPP1." (PMID 38067407, 2023). "Therefore, targeting SPP1+ macrophages may alter the senescent state of tumor cells and reverse immunotherapeutic resistance." (PMID 37090726, 2023). "Therefore, we proposed a hypothesis that the continuous development of PSCC may lead to increased SPP1 gene expression in the tumor microenvironment." (PMID 38111044, 2023).
tumor (continued). "High expression of SPP1 leads to the enhancement of cell migration and adhesion, acceleration of cell growth and division, and abnormal prolongation of cell survival time, which promotes the proliferation, migration, differentiation, and immune escape of tumor cells." (PMID 37251946, 2023). "Building on this understanding, we postulated that HMOX1 expression within a comprehensive tumor gene expression data set could serve as a marker for investigating the influence of microhemorrhage on the development of CD163+ and SPP1+ TAMs, which are implicated in tumor progression." (PMID 38060331, 2023). "Further, in vitro analysis has demonstrated that SPP1 can also inhibit sensitivity to certain chemotherapeutic agents such as doxorubicin and radiotherapy, implying that it might adversely impact tumor response." (PMID 38275392, 2023). "Therefore, activated antitumor immunity and enhanced tumor immunogenicity could explain why high-SPP1 groups are more likely to benefit from antitumor immune activity from the inner immune system than low-SPP1 groups." (PMID 38111044, 2023). "However, there have been no studies distinguishing the SPP1 expression of cancer cells and tumor-associated macrophages (TAMs)." (PMID 36139536, 2022). "Notably, as a ligand originating from SPP1+ macrophages based on the average expression, SPP1 was one of the most abundant ligands in cancerous tissues, implicating a potential connection between SPP1 expression and modulation of the tumor-supportive microenvironment." (PMID 36612160, 2022). "In this study, the expression of VEGFB also gradually increased as the trajectory evolved, and the expression of SPP1, which could promote tumor progression, also increased with the evolution of pseudo time, suggesting that M2 macrophages might promote angiogenesis during the progression of LUAD." (PMID 36046337, 2022). "In addition, the expression level of SPP1 in macrophages was higher than that in cancer cells, and macrophage-derived SPP1 could upregulate downstream target genes, leading to tumor progression and drug resistance in cancer cells." (PMID 36612160, 2022). "Interestingly, the JAK–STAT pathway is the downstream signaling of SPP1,48, 49 and may participate in the SPP1‐mediated tumor progression." (PMID 35593388, 2022). "Furthermore, scRNA-Seq analysis revealed the tumor-promoting role of SPP1+ cells in cancer." (PMID 36078039, 2022). "Collectively, our study reveals that tumor-specific SPP1+ macrophages drive the architecture of intratumor heterogeneity to evolve with tumor progression and that SPP1 may serve as a prognostic marker for advanced GC patients, as well as a potential therapeutic target for GC." (PMID 36612160, 2022). "Moreover, compared to the normal site, SPP1+ TAM exhibited greater enrichment at the tumor site." (PMID 35504878, 2022). "We next tested whether SPP1 could promote the characteristics of tumor stem cells." (PMID 33996808, 2021). "Loss of osteopontin (SPP1) in TAMs, but not glioma cells, enhances tumor progression." (PMID 33766119, 2021). "Importantly, we identified the polyfunctional tumor‐associated myeloid cells, namely SPP1+ TAM subpopulations in CRC, whose functions do not fit the M1 and M2 polarization paradigm." (PMID 34185431, 2021). "Hence, we hypothesized that SPP1 may affect the tumor microenvironment by changing proportions of specific immune cell types, thereby promoting tumor progression and metastasis." (PMID 35058964, 2021). "Importantly, we found that SPP1/CD44 interaction plays a critical role in macrophage-mediated activation of MES-like cells by exploring the cell-cell communication among all cellular components in the tumor ecosystem." (PMID 34805184, 2021). "Pathways enriched in SPP1+Macrophages mainly included processes such as angiogenesis, ECM proteolysis, and tumor-associated fibroblasts, which demonstrated that they could promote tumor metastasis through TME-remodeling." (PMID 34804043, 2021).
tumor (continued). "SPP1 could specifically be expressed by tumor cells and TAMs, thus attracting our attention." (PMID 34804043, 2021). "SPP1 may be involved in the secretion of exosomes of tumor cells." (PMID 32595698, 2020). "However, besides tumor cells, other cells within a tumor microenvironment express SPP1." (PMID 32019108, 2020). "Stromal astrocytes may also contribute to a pool of Spp1 in a tumor microenvironment." (PMID 32019108, 2020). "Indeed, tumor cells can secrete phosphoprotein 1 (SPP1) to induce the expression of PD-L1 in TAMs." (PMID 33224886, 2020). "In addition, SPP1 may also affect the immune escape and malignant biological behavior of tumor cells by regulating EGFR activation." (PMID 32815653, 2020). "Moreover, SPP1 was involved in tumor immunosuppression and influenced the tumor microenvironment." (PMID 33324676, 2020). "These immune-cold CRCs were associated with tumour hypoxia, confirmed using CAIX immunohistochemistry (P = 0.0009), which may mediate disease progression through common biology (KRAS mutations, CRIS-B subtype and SPP1 mRNA overexpression)." (PMID 32684627, 2020). "In addition, tumor cells can also secrete soluble SPP1, which is different from the matrix protein." (PMID 24758329, 2014). "We identified SPP1, secreted by the tumor stroma, as an upstream regulator of the TWIST1-SPON2 cascade via AKT activation in tumor cells in vitro and in vivo." (PMID 41933135, 2026). "Macrophage-derived SPP1, in turn, enhanced DHCR7 expression and 27-HC production in tumor cells via CD44, forming a positive feedback loop that reinforced immune suppression." (PMID 42212157, 2026). "Recent studies identify secreted phosphoprotein 1 (SPP1/osteopontin) as a key NRF2 target frequently overexpressed in cancers, where it drives aggressive tumor behavior, metastasis, chemoresistance, and, in some cases, immune suppression." (PMID 42174609, 2026). "Monocyte subsets 3 and 4 and MG1—the immune populations most enriched within tumor regions—received the strongest incoming signals via tumor-promoting networks such as galectin, complement, TGF-β, SPP1, TNF, and IL-4." (PMID 41503214, 2026). "By defining the role of VISTA in controlling Cxcl9:Spp1 ratio and modulating CD8+ T cell dynamics, this study positions VISTA inhibition as a promising strategy to reshape the TME and potentiate anti-tumor immunity in PDAC." (PMID 41776161, 2026). "SPP1+ TAMs secrete SPP1 to bind CD44 on CD8+ T cells, inducing exhaustion and impairing anti-tumor function." (PMID 41601649, 2026). "Promoter hypomethylation in tumor tissues correlated with overexpression of LAMC2, CTHRC1, CXCL13, FST, SPP1, and PLAU, whereas CDKN2A showed hypermethylation." (PMID 41776121, 2026). "The macrophage lineage was further divided into predominant populations: suppressive (SPP1+, APOC1+), pro-tumour (VEGFA+, MKI67+), inflammatory (C1QC+), classical (CD14+) and non-classical cells (CD16+)." (PMID 39788719, 2025). "In this study, we identify a novel bone–tumor interaction axis in which the BME modulates PKA signaling, promoting SPP1/OPN expression in PCa cells." (PMID 40753365, 2025). "Even though they exhibited consistent tumor-normal dysregulation, five genes (COL12A1, CTSB, PLOD1, SPP1, and SULF1) were excluded from the final candidate list as they did not satisfy the meta-analysis criteria and exhibited loss of prognostic significance." (PMID 41451347, 2025). "These macrophages exhibit elevated expression levels of SPP1 and MARCO (Macrophage Receptor with Collagenous Structure, a scavenger receptor), and their proportion among myeloid cells in tumor samples is significantly higher than that in normal tissues." (PMID 40191203, 2025). "SPP1 has been shown to activate downstream pathways like PI3K/AKT and Rho family small GTPases, enhancing tumor cell adhesion, migration, and invasion." (PMID 40076844, 2025).
tumor (continued). "Regarding CAFs (e.g., α-SMA+ or FAP+ fibroblasts), SPP1 is secreted by certain CAF subsets or induced by CAF-derived factors, mediating cross-talk among CAFs, tumor cells, and macrophages to promote invasion, immune suppression, and therapeutic resistance." (PMID 41391064, 2025). "In mouse models, the use of anti-SPP1 or anti-CD44 antibodies, either alone or in combination with PD-1 antibodies, significantly reduced tumor burden." (PMID 40867844, 2025). "Only regions with enriched macrophages demonstrated a high Pearson correlation coefficient, which indicated that macrophages expressed SPP1 in the TME and interacted with other cell types through the SPP1–CD44 axis in the surrounding area of tumour." (PMID 39934971, 2025). "Further analysis revealed that Pygo2+ CD8+ T cells primarily engage with tumor cells and macrophages through immune checkpoint receptor-ligand pairs, such as CD74, CD55, and SPP1." (PMID 40771810, 2025). "The KC1 subtype exhibited prominent activation of the SPP1 and CRH pathways, aligning with established roles of the CXCL9‐SPP1 macrophage polarity axis in promoting tumour progression and immunotherapy resistance." (PMID 41025426, 2025). "The metastatic TME schematic depicts the coexistence of immunosuppressive (SPP1+ TAMs) and inflammatory (FCN1+ TAMs) macrophage subsets within spatially distinct tumor regions." (PMID 40458409, 2025). "Upon receiving the SPP1 signal from TAMs via the CD44 receptor, tumor cells activate the integrin and phosphodiesterase 3B (PDE3B) pathways, ultimately inducing chemotherapy resistance." (PMID 41341850, 2025). "The roles of SPP1 across various tumor types are systematically summarized in a table, and a schematic figure was generated to depict the major TME components engaged by SPP1 in different malignancies." (PMID 41391064, 2025). "In the context of the crosstalk between tumor cells, stromal cells, and immune cells, the interplay between CD44 and SPP1 has been proposed to suppress CD8 + T-cell activation and foster tumor immune tolerance and evasion." (PMID 40524208, 2025). "Studies have demonstrated that secreted phosphoprotein 1 (SPP1), secreted by TAMs, serves as an intercellular mediator, enhancing the pro‐tumor functions of TAMs, elevating PD‐L1 expression, and sustaining cancer cell stemness." (PMID 40356222, 2025). "Our findings identify several tumor-specific interactions between FAP+ fibroblasts and TAMs, especially SPP1+ macrophages." (PMID 40438108, 2025). "In GSE25097 dataset, compared with normal tissues, the expressions of CDC20, LPCAT1, and SPP1 were significantly upregulated, while PON1 was significantly downregulated in tumor tissues, which was consistent with the results in TCGA." (PMID 40404896, 2025). "Together, SPP1+ macrophages and POSTN+ CAFs form physical and biochemical tumor immune barriers (TIBs) that shield tumor cores from T-cell access and reduce the efficacy of immune checkpoint blockade (ICB) therapies." (PMID 40507341, 2025). "A recent report identified a subset of TAMs, characterised by high expression of SPP1, CD68, CHI3L1, and MT1G, preferentially residing within hypoxic tumour regions, suggesting a role in adaptation to metabolic stress." (PMID 40395129, 2025). "Identifying key signaling pathways and ligand-receptor pairs, such as PSAP-GPR37 and SPP1-(ITGA5+ITGB1), highlights the importance of intercellular communication in modulating tumor behavior." (PMID 39949776, 2025). "Bioinformatics analysis of 43 tumor samples from 14 HCC patients and 14 adjacent control tissues revealed that SPP1+ APOC1+ TAMs highly co-localize with CAFs, and SPP1 binds to ITGF1 secreted by CAFs, collectively remodeling the tumor immune microenvironment." (PMID 40764998, 2025). "The CellTrek mapping analyses effectively visualized the spatial distribution of SPP1+ TAM, STMN2+ TAM, APOE+ TAM, Tregs, CD8+ Tex cells, and Tem/Teffe cells within tumor sections, revealing their substantial infiltration in TIME." (PMID 41438751, 2025).
tumor (continued). "Ligand‒receptor analysis revealed that azvudine predominantly regulated signal transduction from tumor CD4+ T cells to other immune cells through SPP1-(ITGAV + ITGB5) and SPP1-(ITGAV + ITGB1), as well as COL1A1-(ITGA9 + ITGB1), COL1A1-CD44, and COL1A1-SDC4." (PMID 39819859, 2025). "Conversely, SPP1+ macrophages in CRC can promote immune evasion and tumor progression by supporting a desmoplastic tumor structure through interactions with FAP+ fibroblasts." (PMID 41361894, 2025). "SPP1 can engage receptors like CD44, activating NF-κB signaling and establishing a feed-forward loop that sustains macrophage polarization and promotes tumor progression." (PMID 41425545, 2025). "Within the tumor microenvironment (TME), SPP1+ macrophages promote tumor progression by interacting with cancer-associated fibroblasts (CAFs) and helping to form a physical barrier that restricts immune cell infiltration into the tumor core." (PMID 41425545, 2025). "In OSCC, TAMs with specific SPP1 expression activate fibroblasts through SPP1-CD44 and CD155-CD226 interactions, remodeling metastatic lymph nodes to support tumor cell colonization." (PMID 41417432, 2025). "It includes high expression of SPP1 and FN1, two genes that are recognized for their roles in promoting matrix remodeling and tumor invasion." (PMID 41397026, 2025). "To investigate Spp1 expression induced in TAM, initially, we used Spp1tdTomato reporter mice in which MC38‐H2BGFP tumor cells were implanted in dorsal skinfold window chambers." (PMID 39639496, 2025). "For SPP1+ TAMs, they can upregulate PD-L1 expression while promoting TME matrix remodeling to accelerate tumor progression." (PMID 40034694, 2025). "A significant interaction between SPP1 in cluster 1 and CD44 in cluster 4 was observed, consistent with the high SPP1 and CD44 expression at the tumor boundary." (PMID 39862439, 2025). "In order to probe the metastatic tumor burden in a different metastasis model in mice, we injected the RIL175 cells into the spleens of Spp1 KO and WT mice to study a liver metastasis model." (PMID 40335453, 2025). "Hypoxia-driven SPP1 expression promotes macrophage-CAF interactions, stimulating extracellular matrix remodeling and TIB formation, limiting immune infiltration in tumor cores." (PMID 41357522, 2025). "We find several EMT-related genes whose induction in tumor cells by CAFs is suppressed by STING agonism, including SPP1." (PMID 40215177, 2025). "This suggests a potential correlation between SPP1/HMOX1 expression and the degree of tumour malignancy." (PMID 40495644, 2025). "In this context, we detected a significant increase in NGAL, COL1 A1, MMP9, SPP1, TNC and VEGF expression after IL-36 stimulation in HT-29 cells, indicating its potential role in promoting tumour progression through enhanced matrix remodelling." (PMID 40268791, 2025). "A second, frequently recovered interface is SPP1 (osteopontin)–CD44, which is enriched at perivascular niches and couples macrophage programs to mesenchymal tumor traits and treatment resistance." (PMID 41357191, 2025). "At the same time, the latest studies have shown that SPP1 + TAM, as a new macrophage subset, presents a higher immune infiltration rate and has the characteristics of promoting tumor development." (PMID 41384115, 2025). "Considering that these monocytes highly express SPP1 and SPP1+ Macrophages were reported to express immunoglobulin-related genes and monocyte marker VCAN, these cells might be a subset of SPP1+ Macrophages, a kind of tumor-promoting macrophage associated with unfavorable prognosis of patients." (PMID 40755770, 2025). "By binding to receptors such as CD44 and integrins, SPP1 activates key signaling pathways including PI3K/AKT/mTOR, Slug/Snail, MAPK/NF-κB, and Ras/Raf/ERK, thereby promoting tumor cell proliferation, migration, invasion, adhesion, and EMT." (PMID 41384115, 2025).